NLRP3 (NLR family pyrin domain containing 3)
Diseases named in the same sentence as NLRP3 in open-access papers (continued):
Sharing a sentence is not in itself a finding about the gene and the disease.
gout (517 papers, 2007 to 2026). A condition characterized by painful swelling of the joints, which is caused by deposition of urate crystals. "Gouty arthritis (GA) is driven by NLRP3 inflammasome activation, yet its underlying metabolic mechanisms remain poorly explored." (PMID 42137326, 2026). "NLRP3 responds to a variety of stimuli, including the bacterial toxin nigericin, extracellular ATP, and uric acid crystals associated with gout." (PMID 41513612, 2026). "A meta-analysis suggested that patients who are administered diuretics that inhibit NKCC2 increase the level of uric acid in the blood, which is potentially linked to the risk of gout, an NLRP3-associated disease." (PMID 40307577, 2025). "In the context of gouty arthritis, increased levels of Drp1 are implicated in the activation of the NLRP3 inflammasome and associated pathologies." (PMID 40307577, 2025). "The secretion of interleukin-1β (IL-1β), mediated by the NLRP3 inflammasome, plays a pivotal regulatory role in the innate immune responses associated with type 2 diabetes and gout." (PMID 41301787, 2025). "MSU crystals activate the NLRP3 inflammasome, leading to interleukin-1β (IL-1β) release and neutrophil infiltration, causing gouty arthritis." (PMID 41019543, 2025). "MSU is widely accepted as a classical activator of the nucleotide-binding domain and leucine-rich repeat-containing protein 3 (NLRP3) linked to the development of gout." (PMID 39968300, 2025). "Excessive NLRP3 inflammasome activation is associated to numerous inflammatory conditions, including diabetes, Alzheimer's disease, gout, atherosclerosis, and periodontitis." (PMID 41298339, 2025). "Recently the drug Oridonin has been found to have anti-inflammatory properties, and therefore, this can serve as a lead for developing new therapeutics against NLRP3-associated diseases such as peritonitis, gouty arthritis and type 2 diabetes." (PMID 40643515, 2025). "The NLRP3 inflammasome has been implicated in a variety of diseases, including gout, type 2 diabetes, and Alzheimer’s disease." (PMID 40232008, 2025). "Tranilast has beneficial effects on diseases linked to the NLRP3 inflammasome in animal models of gout, type 2 diabetes, and CAPS." (PMID 40079000, 2025). "Activation of the NLRP3 inflammasome has been implicated in the pathogenesis of gout, leading to the production of inflammatory cytokines such as IL-1β, IL-6, and TNF-α." (PMID 39907694, 2025). "The persistent and excessive NLRP3 inflammasome activation is well-established to be closely associated with the gout progression." (PMID 40635741, 2025). "Concurrently, high sociodemographic index (SDI) countries such as Singapore face visceral fat accumulation caused by sedentary lifestyles, activating the NLRP3 inflammasome and triggering chronic inflammation—a critical contributor to gout pathogenesis." (PMID 40720428, 2025). "The NLRP3 inflammasome has been associated with a number of chronic diseases, including diabetes, fibrosis, gout, Alzheimer’s disease, and autoinflammatory diseases." (PMID 38248332, 2024). "Gouty arthritis (GA) is characterized by monosodium urate (MSU) crystal accumulation that instigates NLRP3-mediated pyroptosis; however, the underlying regulatory mechanisms have yet to be fully elucidated." (PMID 38773379, 2024). "The activation of the NLRP3 inflammasome causes the body to produce an abundance of inflammatory factors such as IL-1β, thereby inducing gouty arthritis." (PMID 39544522, 2024). "The NLRP3 inflammasome is implicated in several frequent inflammatory diseases, including gout, rheumatoid arthritis, Crohn’s disease, and, more occasionally, pulmonary fibrosis." (PMID 39195255, 2024). "MSU crystals, which cause gout, induce neutrophil infiltration and IL-1β secretion in an NLRP3 inflammasome-dependent manner when directly injected into the peritoneum." (PMID 39179640, 2024).
gout (continued). "NLRP3 is a widely recognized inflammasome and identified as playing a crucial role in the innate immune response associated with gout." (PMID 39100670, 2024). "Active caspase-1 is well recognized to cleave pro-IL-1β to produce mature IL-1β in the process of NLRP3 inflammasome activation, which is considered a pathogenic mechanism in the pathogenesis of gout." (PMID 39065733, 2024). "Gout is a common inflammatory disease, and gouty attacks are characterized by acute neutrophil-predominant inflammation caused by the activation of NLRP3 inflammasome." (PMID 38633818, 2024). "Among diverse activators, monosodium urate (MSU) is a classical NLRP3 activator linked to the development of gout." (PMID 38371945, 2023). "The inflammatory cascade triggered by MSU crystals is the main cause of the acute symptoms of gout, and the NLRP3 inflammasome pathway is primarily responsible for MSU-induced cellular inflammation." (PMID 37344836, 2023). "Among diseases related to the NLRP3 inflammasome, gout is one of the first diseases pathogenically associated with the inflammasome." (PMID 38371945, 2023). "Another study reported that isoliquiritigenin is a potent inhibitor of NLRP3 inflammasome activation, which is implicated in the etiology of gouty arthritis." (PMID 37881185, 2023). "The activation of the NOD-like receptor thermal protein domain associated protein 3 (NLRP3) inflammasome by MSUc in macrophages and monocytes is closely related to the initiation of gout flares." (PMID 37996809, 2023). "Many common human diseases, such as atherosclerosis, type 2 diabetes, Alzheimer's disease, or gout, have been linked to NLRP3 inflammasomes." (PMID 37300757, 2023). "Uric acid is the main pathogenic trigger in the pathogenesis of gout through NLRP3 inflammasome activation." (PMID 36979628, 2023). "During the inflammatory response of alcoholic liver injury and gouty arthritis, the uncontrolled IL-1β processed by NLRP3 causes the inflammatory response and induces the release of more proinflammatory cytokines and adhesion molecules." (PMID 36176434, 2022). "Several NLRP3 inhibitors have been shown to inhibit inflammation caused by gouty arthritis, emphasizing the importance of NLRP3 as a target in treatments for gout." (PMID 35754962, 2022). "Deletion of a small heterodimer partner caused an excessive NLRP3 response in a mouse model of gout via a mechanism involving severe damage to and accumulation of mitochondria and the sustained action of NLRP3 and ASC." (PMID 35464445, 2022). "Tranilast ameliorates NLRP3 inflammasome-associated diseases in mice, including gouty arthritis, cryopyrin-associated autoinflammatory syndromes, and type 2 diabetes." (PMID 35669789, 2022). "NLRP3 and IL-1β have been identified as risk factors for gout, and it has been clinically confirmed that high levels of NLRP3, Caspase-1, IL-1β and IL-6 have been detected in serum and synovial fluid of patients." (PMID 36313318, 2022). "Elevated levels of NLRP3, IL-1β/-18, the risk factors for gout, are detected in serum and synovial fluid of the gouty patients than those of healthy counterparts." (PMID 36522335, 2022). "3HB was reported to block NLRP3 inflammasome and this deactivation in neutrophil caused by ketone diet relieves gout flares." (PMID 35725651, 2022). "This study focused on oxidative stress, NF-κB signal transduction and NLRP3 inflammation to study the molecular mechanism of P. igniarius on gout-related inflammation caused by MSU crystals in HUVECs." (PMID 36339594, 2022). "The variance in susceptibility to gout is associated with single nucleotide polymorphisms (SNPs) in the NLRP3 inflammasome gene." (PMID 36522335, 2022). "The NLRP3 inflammasome is a cytoplasmic protein complex that is implicated in IL-1β release and inflammation in various inflammatory diseases, including gout." (PMID 36234744, 2022).
gout (continued). "The expression of the inflammasome (TLR4 and NLRP3) is associated with acute gout inflammation, which was determined by western blot, and WPP and CPP inhibited the expression of TLT4 and NLRP3." (PMID 36339594, 2022). "Gallic acid increases the expression of nuclear factor Nrf2 to inhibit the activity of the NLRP3 inflammasome, reduces the release of inflammatory factors, and alleviates gouty arthritis caused by MSU accumulation." (PMID 35411030, 2022). "Toll-like receptor (TLR) and NLRP3 inflammasome activation and the associated inflammatory responses are critical factors in the progression of hyperuricemia to gout." (PMID 35813212, 2022). "Recent studies have shown that the activated NLRP3 inflammasome is closely associated with the inflammatory response in gout." (PMID 36569836, 2022). "knockdown of lncRNA HOTAIR inhibits inflammatory cytokine secretion by increasing the expression of miR-20b and decreasing the expression of NLRP3, thereby relieving ankle swelling caused by gouty arthritis." (PMID 35368701, 2022). "This study clarified the immune response and pathological association of XOD and NLRP3 inflammasome in gout." (PMID 36569836, 2022). "Dysregulation of the nucleotide-binding oligomerization domain, leucine-rich repeat, and pyrin domain-containing protein 3 (NLRP3) inflammasome is associated with the pathogenesis of gout through the maturation of interleukin-1β." (PMID 35400961, 2022). "While these responses are essential for host defense, excessive and uncontrolled NLRP3 inflammasome responses cause and contribute to a wide spectrum of inflammatory diseases, including gout." (PMID 36225929, 2022). "Collectively, we conclude that corilagin alleviates MSU crystals-caused gouty arthritis by restraining NLRP3 inflammasome activation, inflammatory cytokines expression, and immune cell infiltration." (PMID 36299604, 2022). "The NLRP3 inflammasome is a major signaling pathway of the innate immune system, and is associated with gout, atherosclerosis, atrial fibrillation (AF), and other diseases." (PMID 35368226, 2022). "NLRP3 inflammasome upregulation and activation has been found to be associated in the development of many major diseases such as gout, type 2 diabetes, obesity-induced insulin resistance, and depression." (PMID 34092247, 2021). "The excessive deposition of uric acid crystals is usually associated with gout and accompanied by the obvious activation of NLRP3 inflammasomes in the inflammatory disease." (PMID 34459122, 2021). "Tranilast (200 mg/kg) has been documented to increase body weight and survival and to produce demonstrable therapeutic benefits in murine models of NLRP3-induced gouty arthritis, MSU-induced peritonitis, and cryopyrin-associated periodic syndromes (CAPS)." (PMID 34443594, 2021). "It was established that the NLRP3 inflammasome plays a central role in the uncompromising pain associated with gouty arthritis in 2016, and also in arthritic-type components of Chikungunya disease, while recently it has been shown to play a role in migraines." (PMID 34832855, 2021). "In NLRP3 inflammasome-deficient mice, the symptoms of gouty arthritis and pathological markers induced by MSU injection were lessened compared to those of the wild-type control group." (PMID 33534121, 2021). "This suggests an important link between treating blood pressure by targeting the WNK1 pathway and increasing the risk of exaggerating NLRP3-mediated inflammatory diseases such as gout." (PMID 34315884, 2021). "Along with its pathogenic role as a molecular mediator of inflammation, NLRP3’s role is further established by its genetic association with gout." (PMID 33926105, 2021). "Damage-associated molecular patterns (DAMPs) can also activate the NLRP3 inflammasome in gout and increase IL-1β gene expression via activation of toll-like receptors 2 and 4 (TLR2 and TLR4)." (PMID 34992596, 2021).
gout (continued). "Overall, warming attacked joins would reduce the risk of gout attacks by decreasing NLRP3 inflammasome activation." (PMID 34440688, 2021). "In hyperuricemic patients, synergistic action between MSU and ATP is required to fully activate the NLRP3 inflammasome, which causes sufficient secretion of IL-1β, leading to the onset of gout flares." (PMID 34925366, 2021). "Uric acid crystal is known to activate the NLRP3 inflammasome and to cause tissue damages, which can result in many diseases, such as gout, chronic renal injury and myocardial damage." (PMID 32558367, 2020). "Nod-like receptor protein 3 (NLRP3)-mediated pyroptosis has a causal role in the pathogenesis of gout." (PMID 32457291, 2020). "MSU crystals are an important inducer of gouty arthritis, which is closely linked to NLRP3 inflammasome activation and mature IL-1β secretion." (PMID 33365024, 2020). "Tranilast, a tryptophan metabolite analog, binds to NACHT domain of NLRP3, preventing NLRP3-NLRP3 interaction and alleviating the symptoms of gouty arthritis, cryopyrin-associated autoinflammatory syndromes, and type 2 diabetes." (PMID 33603747, 2020). "It is better to confirm the in vivo anti-inflammatory activity of F240B using NLRP3-associated disease models, such as subcutaneous air pouch inflammation model or gout inflammation model by injecting MSU crystals in joints." (PMID 33424855, 2020). "Owing to the interaction of NLRP3 inflammasome and cAMP, we then investigated the effect of adenylate cyclase activator (Forskolin) on macrophage pyroptosis and gout flare caused by MSU stimulation." (PMID 32457291, 2020). "New researches on exogenous activators of NLRP3 inflammasome suggest the role of a purine-rich diet, that is observed to increase 5-fold the risk of an acute attack of gout." (PMID 32426360, 2020). "Mice deficient in NLRP3 fail to produce active IL-1β in the foot pads in response to MSU crystals in an acute gout mouse model." (PMID 31174271, 2019). "Innate immune cell recruitment, inflammatory cytokine release, tissue damage, and remodeling in gout have been linked to the activation of the Nlrp3 inflammasome in response to MSU." (PMID 31803174, 2019). "Caspase-1 and NLRP3 are closely linked to the pathogenesis of various metabolic diseases including gouty arthritis." (PMID 31871475, 2019). "Since then, NLRP3 mutation and hyperactivation have been linked to gout, diabetes type 2, familial Mediterranean fever, and rheumatic disease among many others." (PMID 29861655, 2018). "Rs45520937 of the PPARGC1B gene was associated with gout in a Chinese cohort, and the A allele of this SNP was found to significantly augment the expression of NLRP3 and IL-1β." (PMID 30123371, 2018). "In vivo experiments show that TR has remarkable preventive or therapeutic effects on the mouse models of NLRP3 inflammasome‐related human diseases, including gouty arthritis, cryopyrin‐associated autoinflammatory syndromes, and type 2 diabetes." (PMID 29531021, 2018). "The MSU crystals, while being digested by macrophages, cause a parallel stimulation of the NLRP3 inflammasomes, thereby triggering the excessive release of IL-1β and leading to the pathogenesis of gout." (PMID 29686531, 2018). "Our results demonstrate that NLRP3 inflammasome is the primary target for the action of TR in the mouse models of inflammation‐associated diseases, at least in type 2 diabetes and gouty arthritis." (PMID 29531021, 2018). "In conclusion, our findings indicated that the NLRP3 rs10754558 SNP and its haplotypes were associated with an increased susceptibility to gout." (PMID 29214547, 2018). "In vivo, TR has remarkable preventive or therapeutic effects on the mouse models of NLRP3 inflammasome‐related human diseases, including gouty arthritis, cryopyrin‐associated autoinflammatory syndromes, and type 2 diabetes." (PMID 29531021, 2018).
gout (continued). "The MSU-induced production of IL-1β, which is mediated by the NLRP3 inflammasome activation in macrophages, is a key pathological mechanism underlying gout." (PMID 28376889, 2017). "Recently, basic and clinical research studies have implicated IL-1β and its maturation by the NLRP3 inflammasome in the pathogenesis of gout." (PMID 28167912, 2017). "As endogenous crystals, MSU crystals and calcium pyrophosphate dehydrate (CPPD) crystals are known to activate the NLRP3 inflammasome and cause inflammation in gout and pseudo-gout, respectively." (PMID 29259717, 2017). "Variants rs2043211 (CARD8), rs1143623 (IL1B) and rs2569190 (CD14), which were associated with gout, are functional variations in genes directly involved in the NLRP3 signaling pathway, and as such are likely to represent genuine disease-susceptibility loci." (PMID 26462562, 2015). "Here the authors show that orphan nuclear receptor small heterodimer partner protein (SHP) negatively regulates NLRP3, and its loss leads to accumulation of damaged mitochondria and gout-like immunopathology." (PMID 25655831, 2015). "To date, there are very few studies conducted on the association of NLRP3 polymorphisms and the risk of gouty arthritis." (PMID 25788762, 2015). "In fact, genetic frequency of NLRP3 intronic variant rs7512998 was significantly different between gout and control patients." (PMID 26523150, 2015). "Mechanistically, studies have shown that dysregulation of the signaling cascade is associated with gout, while the circadian clock can regulate the expression and activation of NLRP3, thereby controlling the secretion of IL-1β and IL-18 in various tissues and immune cells, particularly macrophages." (PMID 40495130, 2025). "The NLRP3 inflammasome has been extensively investigated in joint diseases where inflammasome activation is a central pathogenic mechanism, with initial translational evidence emerging in gout and osteoarthritis (OA)." (PMID 40869653, 2025). "The pathogenic mechanism of NLRP3 inflammasome activation in gout is not well understood." (PMID 40874164, 2025). "The activation of the NLRP3 inflammasome, facilitated by the dysregulation of calcium homeostasis in macrophages, represents a critical component of inflammation associated with gout." (PMID 41301787, 2025). "However, recent genome-wide association studies (GWAS) in gout have revealed new pathogenic pathways, for example, genes involved in NLRP3 inflammasome activation and activity, and genes involved in clonal hematopoiesis of indeterminate potential." (PMID 40874164, 2025). "Although the association between mitochondria function and NLRP3-associated inflammations, including gout and cardiovascular events, has been reported, it remains controversial because NAD+, which reflects mitochondrial internal respirational function, was not measured in this study." (PMID 38397902, 2024). "Previous studies have suggested that CY-09 could be used for the treatment of NLRP3 inflammasome-associated diseases, including type 2 diabetes, gout, thrombosis, cryopyrin-associated autoinflammatory syndrome (CAPS) mouse models, and other diseases." (PMID 38892264, 2024). "Moreover, several studies have found that certain NLRP3 polymorphisms, most notably rs3806268 and rs10754558, were associated with an increased susceptibility to gout." (PMID 37598797, 2023). "Among them, the rs3806268 AG genotype was significantly associated with decreased risk of gout, and the T-allele of rs3738448 may enhance the stability of NLRP3 mRNA, thereby increasing the risk for GA." (PMID 37051231, 2023). "In addition to the NLRP3-related pathway, more than 200 genes have been suggested to be dysregulated in gout patients; these genes are mainly associated with inflammation, cytokines, and chemokine activation." (PMID 38201364, 2023).